THSD1 (thrombospondin type 1 domain containing 1)
Description:
Is a positive regulator of nascent focal adhesion assembly, involved in the modulation of endothelial cell attachment to the extracellular matrix.
Synonyms: TMTSP; ANIB12; LMPHM13; UNQ3010
Tractability: Antibody: UniProt places it where antibodies can reach, with high confidence; UniProt predicts a signal peptide or a membrane-spanning region; its Gene Ontology location is reachable by antibodies, with medium confidence.
Gene: Protein-coding gene on chromosome 13 (52,377,163 to 52,416,373, reverse strand). Ensembl gene ENSG00000136114.
Subcellular location: Endosome membrane (Isoform 1); Cell junction, focal adhesion; Membrane (Isoform 2); Secreted (Isoform 3)
Subcellular location (Human Protein Atlas): Cytosol
Pathways (Reactome):
Disease: Defective B3GALTL causes PpS
Metabolism of proteins: O-glycosylation of TSR domain-containing proteins
Gene Ontology:
Molecular function: extracellular matrix binding; protein binding
Biological process: focal adhesion assembly
Cellular component: cytosol; endosome; endosome membrane; focal adhesion; cell periphery; cytoplasm; extracellular region; membrane
Genetic constraint (gnomAD): Loss-of-function variants: 34 observed, 52.59 expected, observed/expected ratio (o/e) 0.65, 90% interval 0.49 to 0.86. The upper end of that interval is the gene's LOEUF score, 0.86, which puts it in group 3 of 6, group 1 being the genes least tolerant of losing a copy. Missense variants: 1,021 observed, 1,103 expected, observed/expected ratio (o/e) 0.93, 90% interval 0.88 to 0.98. Synonymous variants: 407 observed, 438.47 expected, observed/expected ratio (o/e) 0.93, 90% interval 0.86 to 1.01.
Homologues: Orthologues: chimpanzee THSD1 (99% identical), macaque THSD1 (96% identical), rabbit THSD1 (85% identical), guinea pig THSD1 (85% identical), pig THSD1 (82% identical), dog THSD1 (81% identical), mouse Thsd1 (79% identical), rat Thsd1 (78% identical), tropical clawed frog thsd1 (45% identical), zebrafish thsd1 (7% identical).
Diseases named in the same sentence as THSD1 in open-access papers:
THSD1 is named in the same sentence as 28 diseases in open-access papers, as found by Europe PMC text mining. Sharing a sentence is not in itself a finding about the gene and the disease. The quoted sentences say what the papers report.
colorectal cancer (5 papers, 2010 to 2023). A primary or metastatic malignant neoplasm that affects the colon or rectum. "Downregulation of THSD1 is correlated with its methylation in colorectal cancer cell lines, and the gene encodes a transmembrane molecule thought to be involved in cell adhesion and angiogenesis with its loss being associated with metastatic tumor spread in breast cancer." (PMID 33302475, 2020). "In colorectal cancer, THSD1 is down-regulated and methylated in the promoter region, but the expression of THSD1 in gastric cancer with peritoneal metastasis and its role in turmorigenesis are not yet known." (PMID 27270314, 2016). "In addition, the current study identified THSD1 down-regulation and methylation in primary colorectal cancer (CRC) tissues." (PMID 37139087, 2023). "THSD1 is methylated and down regulated in colorectal cancer and esophageal squamous cell carcinoma." (PMID 26822197, 2016). "Ten of these genes (WDR67, RFXAP, RP11-50D16.3, CAB39L, THSD1, SPRY2, TGDS, CLDN10, SLC10A2, CD33L3) have been reported changed in tumor tissues, while only 2 (RP11-50D16.3, SLC10A2) have been reported to appear changed in colorectal cancer." (PMID 20467480, 2010).
cerebrovascular disease (3 papers, 2020 to 2024). "Multiple rare variants in the THSD1 gene have been identified in patients with intracranial aneurysms, a type of cerebrovascular disease." (PMID 38396816, 2024). "A recent study also supports the role of variants in THSD1 as susceptibility factors for cerebrovascular disease." (PMID 37139087, 2023). "Our data support a role of sequence variants in PCNT, RNF213 and THSD1 as susceptibility factors for cerebrovascular disease." (PMID 32367296, 2020). "Interestingly, multiple harmful rare variants in the THSD1 gene have been identified in patients with intracranial aneurysms—a cerebrovascular disorder characterized by the weakening of blood vessel walls." (PMID 38396816, 2024). "This study investigates the role of Thrombospondin Type 1 Domain-Containing Protein 1 (THSD1) in regulating autophagy and FA stability in brain endothelial cells, shedding light on its potential implications for cerebrovascular diseases." (PMID 38396816, 2024).
esophageal squamous cell carcinoma (3 papers, 2016 to 2025). Esophageal squamous cell carcinoma (ESCC) is a type of esophageal carcinoma (EC) that can affect any part of the esophagus, but is usually located in the upper or middle third. "Overexpression of THSD1 in esophageal squamous cell carcinoma cell lines inhibits colony formation, suggesting a tumor-suppressive function." (PMID 40564011, 2025). "In colorectal cancer and esophageal squamous cell carcinoma cell lines, THSD1 expression is significantly downregulated, potentially through promoter methylation." (PMID 40564011, 2025). "THSD1 was proved as a novel candidate tumor suppressor gene for esophageal squamous cell carcinoma." (PMID 34020650, 2021).
intracranial aneurysms (3 papers, 2023 to 2025). "THSD1 variants or gene loss probably cause intracranial aneurysms (IA) and SAH." (PMID 37139087, 2023). "The most extensively studied role of THSD1 is in maintaining vascular integrity, particularly in the context of intracranial aneurysm (IA) and subarachnoid hemorrhage, conditions characterized by weakening and rupture of the cerebral artery wall." (PMID 40564011, 2025). "The influence of THSD1 extends beyond intracranial aneurysms to other vascular contexts." (PMID 40564011, 2025). "Further investigations into the mechanisms by which THSD1 influences these processes may provide valuable insights into the development and progression of vascular diseases such as intracranial aneurysms, potentially unveiling novel therapeutic targets for intervention." (PMID 38396816, 2024).
nonimmune hydrops fetalis (3 papers, 2015 to 2025). "THSD1 has also been implicated in nonimmune hydrops fetalis (NIHF), a serious perinatal disorder characterized by abnormal fluid accumulation in the fetus or newborn." (PMID 40564011, 2025). "THSD1 mutations have also been linked to perinatal disorders such as nonimmune hydrops fetalis and congenital vascular anomalies, suggesting a broader role in embryonic vascular patterning." (PMID 40564011, 2025). "A case series in UAE shows the THSD1 variant causes intracranial berry aneurysm 12, nonimmune hydrops fetalis, congenital cardiac defects, hemangiomas and hypogammaglobulinemia." (PMID 33481921, 2021). "Beyond the genetic association, recent clinical analyses suggest that THSD1 deficiency may disrupt fetal vascular integrity and lymphatic development, potentially contributing to fluid imbalance in nonimmune hydrops fetalis." (PMID 40564011, 2025). "Given THSD1’s role in focal adhesion and autophagy regulation in endothelial cells, similar pathways may underline the pathophysiology of nonimmune hydrops fetalis." (PMID 40564011, 2025). "Unlike the other six candidate genes, we were able to identify a second mutation in THSD1 in a family with a less severe phenotype consisting of hydrops fetalis and persistent postnatal edema, which provides further support for the proposed link between this gene and embryonic lethality." (PMID 26036949, 2015).
esophageal cancer (2 papers, 2016 to 2023). A primary or metastatic malignant neoplasm involving the esophagus. "In 2010, the tumor-suppressive and angiogenic role of THSD1 in esophageal carcinoma cells was reported, and THSD1 is a critical tumor-suppressive region in esophageal carcinoma." (PMID 37139087, 2023). "THSD1 is located in the chromosome 13q region that is frequently lost in esophageal cancer, accelerating cancer formation." (PMID 27270314, 2016).
gastric cancer (2 papers, 2016 to 2025). A primary or metastatic malignant neoplasm involving the stomach. "THSD1 mutations have been identified in gastric cancer and are associated with unfavorable survival outcomes." (PMID 40564011, 2025). "THSD1, which is mutated in both the primary gastric cancer and peritoneal metastasis, has a mutation frequency of 5.4%(21/389) in gastric adenocarcinoma in the COSMIC database." (PMID 27270314, 2016). "Large-scale proteomic studies by two independent groups have confirmed that THSD1 serves as a robust biomarker for gastric cancer." (PMID 40564011, 2025).
hemangioma (2 papers, 2021 to 2025). A benign vascular lesion characterized by the formation of capillary-sized or cavernous vascular channels. "In this regard, THSD1 could serve as a potential diagnostic marker or therapeutic target in select cases of unexplained hydrops, especially when accompanied by vascular malformations or hemangiomas." (PMID 40564011, 2025).
lung carcinoma (2 papers, 2018 to 2022). "Low expression of THSD1 existed in the tumor parts, lymph node metastasis and tumor stage compared with the normal parts in lung cancer patients." (PMID 35743687, 2022).
atherosclerosis (1 paper, 2025). A disease characterized by the build-up of fatty material and calcium deposition in the arterial wall resulting in partial or complete occlusion of the arterial lumen. "In atherosclerosis, THSD1 expression is downregulated by pro-atherogenic factors such as TNFα and upregulated by the anti-atherogenic cytokine IL-10, suggesting a dynamic regulatory role in atherosclerosis prevention." (PMID 40564011, 2025). "Furthermore, in an ApoE knockout mouse model of advanced atherosclerosis, THSD1 overexpression reduces intraplaque hemorrhage by 45%, accompanied by decreased macrophage infiltration and necrotic core size." (PMID 40564011, 2025).
diabetes (1 paper, 2023). "Furthermore, the THSD1 rs3803264 variant had significantly associated with the reduced risk of HS in subgroups of age less than or equal to 65 years, males, hypertension, non-diabetes, and non-dyslipidemia." (PMID 37139087, 2023).
dyslipidemia (1 paper, 2023). "Interaction analysis of THSD1 rs3803264 and dyslipidemia with the risk of hemorrhagic stroke in the case–control study." (PMID 37139087, 2023). "Furthermore, we observed THSD1 rs3803264 significantly interacted with dyslipidemia in the risk of HS." (PMID 37139087, 2023). "THSD1 rs3803264 and dyslipidemia had a positive interaction, specifically high levels of TC and LDL-C." (PMID 37139087, 2023). "The multiplicative interaction analyses indicated that THSD1 rs3803264 and dyslipidemia had a positive interaction, specifically in the high level of TC and LDL-C groups." (PMID 37139087, 2023). "SNP rs3803264 polymorphisms in THSD1 are associated with the decreased risk of HS and interacted with dyslipidemia, and a non-linear association was observed between THSD1 mRNA expression and the risk of HS." (PMID 37139087, 2023). "In addition, THSD1 rs3803264 and dyslipidemia had a positive interaction." (PMID 37139087, 2023). "Thus, our results demonstrated that tag rs3803264 of THSD1 polymorphism was associated with the decreased risk of HS and interacted with dyslipidemia, and a non-linear association was observed between THSD1 mRNA expression and the risk of HS." (PMID 37139087, 2023).
gastric adenocarcinoma (1 paper, 2016). "In the COSMIC database, THSD1 was mutated in 5.4% (21/389) of gastric adenocarcinoma." (PMID 27270314, 2016).
hemorrhagic stroke (1 paper, 2023). A stroke caused by a bleed on the brain. "Association analyses of THSD1 rs3803264 with the incidence risk of hypertension and hemorrhagic stroke in the cohort study." (PMID 37139087, 2023). "We sought to characterize the association of THSD1 genetic variants and mRNA expression with the risk of hemorrhagic stroke (HS) with population-based evidence." (PMID 37139087, 2023). "Therefore, we conducted a case–control and cohort study to investigate the association of THSD1 genetic variants and mRNA expression with the risk of hemorrhage stroke." (PMID 37139087, 2023).
Hypertension (1 paper, 2023). The presence of chronic increased pressure in the systemic arterial system. "For the subjects without hypertension, we observed THSD1 mRNA expression had a negative correlation with SBP (ρ = −0.334, p = 0.022)." (PMID 37139087, 2023). "For the subjects without hypertension, we observed THSD1 mRNA expression had a negative correlation with systolic blood pressure (SBP; ρ = −0.334, p = 0.022)." (PMID 37139087, 2023). "While for all subjects without hypertension, we observed THSD1 mRNA expression had a negative correlation with SBP." (PMID 37139087, 2023). "For the subjects without hypertension, we observed THSD1 mRNA expression had a negative correlation with SBP." (PMID 37139087, 2023). "There was no significant linear correlation of THSD1 mRNA expression with clinical indicators (GLU, TC, TG, HDL-C, LDL-C, SBP, and DBP) in all subjects, controls, or HS cases, no matter whether they have hypertension or not (all p > 0.05)." (PMID 37139087, 2023).
intracranial hemorrhage (1 paper, 2025). Bleeding within the SKULL, including hemorrhages in the brain and the three membranes of MENINGES. "Interestingly, intracranial hemorrhage has been observed in two THSD1-deficient vertebrate models—zebrafish and mice—with the hemorrhage localized to the subarachnoid space in the latter." (PMID 40564011, 2025).
lung adenocarcinoma (1 paper, 2019). A carcinoma that arises from the lung and is characterized by the presence of malignant glandular epithelial cells. "Additionally, recent study revealed that DAPK2, MFSD2A, THSD1 and WNT7A were oncogenes which showed high expression and low methylation in lung adenocarcinoma." (PMID 30899432, 2019).
lymphedema (1 paper, 2015). Excess fluid collection in tissues, causing swelling. "In the case of THSD1, it appears that mutations in this gene cause a range of Mendelian phenotypes ranging from a lethal form of NIHF to self-limited lymphedema that resolves with age." (PMID 26036949, 2015).
nail disorder (1 paper, 2021). A disease involving the nail. "Remarkably, this family has multiple members with the classical FZD6-related nail disorder with history of NIHF during pregnancy, which suggests that FZD6-related NIHF, like THSD1-related NIHF, can be compatible with long-term survival if mortality in the newborn period is avoided." (PMID 34645488, 2021).
Perinatal Disorders (1 paper, 2025). "Although these clinical observations strongly implicate THSD1 in developmental and perinatal disorders, the underlying molecular mechanisms remain incompletely understood." (PMID 40564011, 2025).
retinoblastoma (1 paper, 2020). A malignant tumor that originates in the nuclear layer of the retina. "The THSD1 gene is often mutated in cancer and was found to be duplicated in a patient with unilateral retinoblastoma (1N13), lacking an RB1 mutation." (PMID 32577795, 2020).
tumor (10 papers, 2010 to 2025). "Collectively, these observations suggest that THSD1 may serve as a diagnostic and prognostic biomarker across multiple cancer types and may function as a tumor and metastasis suppressor, although the underlying molecular mechanisms remain to be fully elucidated." (PMID 40564011, 2025). "Recent mechanistic studies further elucidate THSD1’s role as a tumor suppressor and therapeutic target." (PMID 40564011, 2025). "In addition to its regulatory effects on focal adhesions, THSD1 appears to modulate the tumor microenvironment by influencing vascular stability and immune cell infiltration." (PMID 40564011, 2025). "Moreover, emerging evidence indicates that THSD1 acts as a tumor and metastasis suppressor, with potential anti-angiogenic properties, although its role in cancer remains to be fully defined." (PMID 40564011, 2025). "The common pathological processes of angiogenesis in tumor enlightened the researchers that whether THSD1 also play a significant role in intracerebral hemorrhage." (PMID 37139087, 2023). "THSD1 is downregulated in A549 cells and other cancer cell lines, and may function as a tumor suppressor, but its role in cancer and interaction with other genes is not well understood." (PMID 33302475, 2020). "Another study using monochromosome transfer and microarray analysis demonstrated that transfection of wild-type THSD1 into SLMT-1 cells significantly reduced colony-forming ability, providing functional evidence for its tumor-suppressive activity." (PMID 40564011, 2025). "Therefore, our data suggests that unlike cisplatin, phenanthriplatin treatment might act to prevent the action of THSD1 in some cancers eliminating its role as a tumor suppressor, but the reason for the distinct action of the monofunctional complex compared to cisplatin on THSD1 is not clear." (PMID 33302475, 2020). "While THSD1 does not directly affect neovascular growth in zebrafish or murine retina models, its role in maintaining vascular integrity may indirectly influence tumor vasculature and microenvironment." (PMID 40564011, 2025). "In our two analyzed gene loci (THSD1 and GSTT2), no aberrant methylation in patients was detected in contrast to hypermethylation in the analyzed tumor cell lines." (PMID 32577795, 2020).
cancer (7 papers, 2016 to 2025). A tumor composed of atypical neoplastic, often pleomorphic cells that invade other tissues. "These functional insights, together with clinical expression data, strengthen the case for THSD1 as a diagnostic and prognostic biomarker in human cancers." (PMID 40564011, 2025). "These variants were found in genes associated with cancers (ANKRD35, DNAH9, MAGEC1, TOX3) or participating in cancer-related signaling pathways (THSD1, MORN2, PTCRA)." (PMID 26822197, 2016). "Some studies have directly assessed the clinical relevance of THSD1 in cancer cohorts." (PMID 40564011, 2025). "Nonetheless, the definitive role of THSD1 in cancer biology remains to be elucidated." (PMID 40564011, 2025). "Emerging evidence suggests that THSD1 plays a role in tumorigenesis across multiple cancer types." (PMID 40564011, 2025). "Since THSD1 suppresses autophagy-mediated focal adhesion turnover, this mechanism may also be exploited by cancer cells for migration and metastasis." (PMID 40564011, 2025). "We analyzed the expression profile of THSD1 in three independent controls (0N) and six patient-derived fibroblast cell lines (three 1N and three 2N) using qPCR and detected highly variable expression changes after radiation among controls as well as cancer patients (1N, 2N)." (PMID 32577795, 2020). "The finding in a 1N patient of duplicated CKAP2, THSD1, and VPS36 genes in 13q14.3 is very interesting because CKAP2 is responsible for spindle bipolarity and chromosome stability and may represent a new factor contributing to eye tissue cancer development." (PMID 32577795, 2020). "Analysis of methylation levels of THSD1 and GSTT2 genes which were detected in duplicated regions and are frequently aberrantly methylated in cancer showed no changes in patient’s fibroblasts." (PMID 32577795, 2020).
THSD1 also shares sentences with these, for which no sentence is quoted: breast carcinoma (1 paper); hypogammaglobulinemia (1); Infertility (1); intracranial berry aneurysm (1); metastatic tumor (1).